PCNA (proliferating cell nuclear antigen)
Diseases named in the same sentence as PCNA in open-access papers (continued):
Sharing a sentence is not in itself a finding about the gene and the disease.
prostate carcinoma (continued). "In addition, activation of GPRC6A stimulated prostate cancer cell line proliferation and migration, whereas editing GPRC6A in PC-3 cells reduced cell proliferation and transcription of PCNA and c-Fos." (PMID 28659174, 2017). "The reduction of the proliferation on prostate cancer cells and tumor weight from xenografted PC3 may be reflected on the expression levels of PCNA." (PMID 27448980, 2016). "One study found that TRPV6 mediates Ca2+ uptake into prostate cancer cell, subsequently activating downstream nuclear factor of activated T cells (NFAT) to promote the proliferation rate, and proliferating cell nuclear antigen (PCNA) expression." (PMID 26818094, 2016). "The same strategies may also be applied for prostate cancer, but not another common andrological disorder, NOA, which is caused by the impairment of spermatogenesis and needs a way to enhance PCNA activity in spermatogonia." (PMID 34721621, 2021). "Similarly, correlations of clinical toxicity scores from prostate cancer donors were performed with G2 scores and gene expression of each individual gene PCNA, FXDR, CDKN12 and SESN1 using the non-parametric Spearmans correlation test." (PMID 34638945, 2021). "In prostate cancer tissues, a moderate and significant correlation has been observed between DKC1 and MKI67 mRNA levels, but not with PCNA mRNA." (PMID 22912812, 2012).
hepatocellular carcinoma (48 papers, 2011 to 2025). A malignant tumor that arises from hepatocytes. "Proliferating cell nuclear antigen (PCNA) is associated with the proliferation and recurrence of various cancers, and its high expression is associated with poor prognosis in hepatocellular carcinoma (HCC) patients." (PMID 40313621, 2025). "In hepatocellular carcinoma, PCNA, along with cell cycle regulators GTSE1, CDC20, and MCM6, was found to drive tumor progression and predict poor prognosis, establishing PCNA as a potential molecular biomarker for liver cancer." (PMID 41170373, 2025). "Studies have shown that TNFAIP1 mediates DNA replication, repair, and cell cycle regulation by interacting with PCNA, and it regulates hepatocellular carcinoma progression by interacting with CSNK2B." (PMID 37886961, 2023). "Regarding the impact of EGb 761 on PCNA expression, Chao and Chu found that G. biloba extract can significantly suppress PCNA expression in human hepatocellular carcinoma cells." (PMID 36080365, 2022). "The abundance of PCNA protein in both hepatoma cell lines was clearly down‐regulated in ADAM8 knockdown cells compared to the respective controls." (PMID 33314720, 2021). "A study done by Long and Li showed the reduction of PCNA expression by an alkaloidal fraction from aerial parts of Oxytropis ochrocephala in mice hepatocellular carcinoma." (PMID 34237060, 2021). "They inhibited blood vessel growth of tumor through reducing the VEGF expression level in H22 hepatoma-bearing model mice and also inhibited tumor cell proliferation through reducing the PCNA expression." (PMID 33163082, 2020). "Meanwhile, we observed that PCNA was able to enhance the proliferation of hepatoma cells and miR-154 had the reversed effect in the system." (PMID 31410212, 2019). "Most of these nodules also displayed markedly decreased reticulin staining (Reticulin) and elevated frequency of Ki-67 and PCNA staining (Ki-67 and PCNA), indicating that they are indeed hepatocellular carcinoma." (PMID 31754457, 2019). "Conversely, the inhibitor of miR-154 led to the opposite results, supporting that miR-154 can target PCNA in hepatoma cells." (PMID 31410212, 2019). "Our data showed that PCNAP1/PCNA signaling significantly promoted the growth of hepatoma cells in vitro and in vivo." (PMID 31410212, 2019). "Hepatoma cells exhibit vigorous proliferation activity, and PCNA can be used as an indicator of the state of cell proliferation." (PMID 23737842, 2013). "Some clinicopathological studies have identified positive correlations between nuclear survivin expression and various parameters of growth fraction (MIB-1, PCNA and mitotic indices) in hepatocellular carcinoma [reviewed in 4]." (PMID 22075440, 2011). "FAT10 and PCNA expression is high in hepatocellular carcinoma tissues; however, the FAT10 expression is reduced in regenerated liver tissues, while PCNA expression is elevated, thus suggesting that the association between FAT10 and PCNA expression is only exhibited in tumor tissues." (PMID 36386217, 2022). "In addition, USP10 can stabilize proliferating cell nuclear antigen (PCNA) through deubiquitination to enhance the proliferation and migration of hepatoma cells." (PMID 35875077, 2022). "One study noted that PCNA expression was upregulated in hepatocellular carcinoma patients." (PMID 35383533, 2022). "For example, coculture of MSCs with hepatoma cells results in an increase in tumor cell apoptosis and decrease in proliferation by down-regulating Bcl-2, c-Myc, proliferating cell nuclear antigen (PCNA), and survivin protein levels in hepatoma tumor cells; all of them are targets of Wnt signaling." (PMID 32793565, 2020). "The CAt extract reduced the expression of the PCNA protein, suggesting that it might possess the ability to affect cell cycle progression in hepatoma cells." (PMID 33050385, 2020).
hepatocellular carcinoma (continued). "In another study, mouse hepatoma cells treated with 30% ethanol extracts of CN in low or high doses showed a significant decrease in the expression of PCNA and p-AKT (proliferation markers) and increased expression of BAX, Bcl2, caspase-3, and PAPR (apoptosis markers)." (PMID 30806066, 2019). "As expected, we found that PCNAP1 sponged miR-154 to stimulate PCNA expression in hepatoma cells." (PMID 31410212, 2019). "Thus, we conclude that PCNAP1 and PCNA significantly promotes the growth of hepatoma cells in vitro and in vivo." (PMID 31410212, 2019). "Given that the pseudogenes played multiple roles through modulating their ancestral genes 12, we concerned whether the pseudogene PCNAP1 modulated its ancestor PCNA in hepatoma cells." (PMID 31410212, 2019). "Accordingly, we concerned whether PCNAP1 could promote the proliferation of hepatoma cells through modulating the expression of miR-154 and PCNA." (PMID 31410212, 2019). "To determine the impact of these nuclear inclusions on cell fate, we assessed cell proliferation by performing quantification of PCNA staining of HBsAg-Tg mice at 9 months of age, when the maximum vacuolated nuclei were observed and prior to the onset of hepatocellular carcinoma in this model." (PMID 24932583, 2014). "Emodin may treat hepatocellular carcinoma by inhibiting the expression of PCNA." (PMID 39346898, 2024). "However, most striking of all was our finding that malignant tumors, most of which were moderately differentiated hepatocellular carcinomas (HCCs) with solid or trabecular growth patterns that stained strongly for PCNA and phospho-Rps6Ser235/6, developed in ~50% of ΔS6 livers by ~1 year of age." (PMID 36656901, 2023). "In another study on rat hepatocellular carcinoma (HCC), borax (4 mg/kg/day; Bx) treatment reduced Proliferating Cell Nuclear Antigen (PCNA) expression and [3H]-thymidine incorporation as markers of cell proliferation." (PMID 37372032, 2023). "For example, depletion of CBX4 reduces the levels of proliferating cell nuclear antigen (PCNA) and cyclin E2/CCNE2 while increasing the level of cyclin-dependent kinase inhibitor 2A (CDKN2A/p16) to delay the G1/S transition in hepatocellular carcinoma cells." (PMID 38994031, 2024). "The known mRNA interactors of miR-122 include PKM2, AKT1, MYC, TGFBR1, and SMAD4 in hepatocellular carcinoma, JNK, AP1, and caspases 3/8 in irritable bowel disease, and AKT, PI3K, PCNA, MTDH, PI3K, TRIM29, Bcl-W, CCNG1, and ALDO2 in CRC." (PMID 36499586, 2022). "Petroleum ether extracts prepared from the leaves and stems of C. sappan reduced the expression of PCNA and VEGF in the tumors of H22 hepatoma-bearing mice." (PMID 34257693, 2021). "The results of immunohistochemical staining of PCNA and CCK-8 cytotoxicity assay showed that the proliferation of H22 hepatocellular carcinoma cells was inhibited in vivo and in vitro." (PMID 32140106, 2020). "Analysis of tissue immunofluorescence unveiled a substantial correlation between STAMBPL1 expression and the presence of PCNA and Ki67 in both hepatocellular carcinoma (HCC) tissue and adjacent non-cancerous tissues." (PMID 38419066, 2024). "To address whether the PCNA pseudogenes were subjected to HBV expression, we prepared total RNAs from HBV-negative (HBV-) hepatoma cells (HepG2, HepaRG and HepAD38) and HBV-expressing (HBV+) hepatoma cells (termed as HepG2*/HepaRG*/HepAD38* and HepG2.2.15)." (PMID 31410212, 2019). "Thereby, we concerned whether PCNAP1/PCNA signaling, as a regulating factor of HBV replication and cccDNA accumulation, could promote the proliferation of hepatoma cells." (PMID 31410212, 2019). "Hepatoma cells (SK-Hep1 and Huh 7) transfected with ISX shRNAi showed significant downregulation of E2F1 and DP1 protein expression as well as of proliferation markers (cyclin D1, c-Myc, Cdc25A, and PCNA) and anti-apoptotic genes (p65 and Mcl-1)." (PMID 27175585, 2016).
hepatocellular carcinoma (continued). "Hematoxylin and eosin (H & E) staining and TUNEL assay revealed that hepatoma cells underwent significant apoptosis with CN30 treatment, while expression levels of proliferation markers PCNA and p-AKT were significantly decreased when treated with low or high doses of CN30 treatment." (PMID 26393569, 2015).
pancreatic cancer (43 papers, 2009 to 2025). "Overexpression of CST1 was also correlated with malignancy-associated proteins such as PCNA, cyclin D1, cyclin A2 and cyclin E in pancreatic cancer cell line." (PMID 26569312, 2015). "Further, we also validated two additional relevant proteins, HIF1α and PCNA, due to their well-established association with pancreatic cancer progression." (PMID 25929337, 2015). "PCNA has been associated with poor outcomes in pancreatic cancer, and studies have suggested that its phosphorylation status may be a potential biomarker for predicting chemotherapy response." (PMID 40051490, 2025). "Inhibition of miR-324-5p or overexpression of KLF3 in pancreatic cancer cells led to reduced proliferation and increased apoptosis, as shown by decreased levels of proliferating cell nuclear antigen (PCNA) and increased levels of BCL2-associated X (BAX), respectively." (PMID 37239940, 2023). "This suggests that OCT4 may be implicated in the development of pancreatic cancer through AKT pathway-mediated PCNA and MMP-2 expression." (PMID 25017645, 2014). "Furthermore, scatter plot analyses showed significant positive correlations of SET/CIP2A expression with the expression levels of the IEGs (TRIB1, SPRY4, CTGF) and with those of growth-promoting genes (cyclin D1, E2, and PCNA) in KRAS-mutated pancreatic cancers." (PMID 36463234, 2022). "The use of proliferative markers such as Ki‐67, Cyclin D1, PHH3, and PCNA has garnered increasing attention for their potential as prognostic and predictive tools in cancer treatment, including pancreatic cancer." (PMID 40051490, 2025). "Incorporating biomarkers such as Ki‐67, cyclinD1, PHH3, and PCNA into clinical practice for the management of pancreatic cancer poses several challenges." (PMID 40051490, 2025). "Overall, Ki‐67, Cyclin D1, PHH3, and PCNA biomarkers can potentially improve pancreatic cancer clinical management by providing valuable information about disease progression and treatment response." (PMID 40051490, 2025). "The incorporation of proliferative markers like Ki‐67, PCNA, and Cyclin D1 into treatment decision‐making for pancreatic cancer is promising but comes with significant limitations that restrict their current clinical utility." (PMID 40051490, 2025). "Ki‐67, PCNA, and Cyclin D1 offer valuable insights into pancreatic cancer biology and PanIN progression." (PMID 40051490, 2025). "The result indicated that PCNA is remarkably overexpressed in pancreatic cancers compared to normal pancreas." (PMID 40051490, 2025). "Increased PCNA levels provide important information about the biological features of pancreatic tumors by indicating active cell proliferation." (PMID 40051490, 2025). "Since Ki‐67, Cyclin D1, PHH3, and PCNA are key proliferative markers in pancreatic cancer, our review focuses extensively on them." (PMID 40051490, 2025). "GW3965 inhibits the expression of genes involved in pancreatic cancer proliferation such as proliferating cell nuclear antigen (PCNA), downregulated p-S6K1 and induced apoptosis, and upregulates ATF4 and TXNIP." (PMID 38550382, 2024). "Taken together, our results suggested that PAFAH1B3 can upregulate PCNA expression in pancreatic cancer cells to promote their proliferation." (PMID 38649699, 2024). "Our results showed that PROK1 knockdown inhibited pancreatic tumor growth in vivo and reduced proliferating markers, such as PCNA and cyclin D1, at the molecular level." (PMID 37070074, 2023). "PROK1 knockdown also inhibited the proliferation of pancreatic cancer cells, characterized by a decrease in PCNA and cyclin D1 levels, leading to slow growth of PC in vivo." (PMID 37070074, 2023). "Consistent with primary pancreatic tumors, IHC staining was positive for PCNA and pERK in these metastases." (PMID 36650523, 2023).
pancreatic cancer (continued). "In Zinczuk’s study describing Ki67 and PCNA expression in pancreatic cancer, direct correlations between these proteins are demonstrated, revealing that an increase in the expression of one protein results in an increase in the expression of the other." (PMID 36077614, 2022). "Similar research investigated that curcumin alone or in combination with gemcitabine can suppress abnormally expressed PCNA in pancreatic cancer cells." (PMID 33980898, 2021). "A previous study also indicated that Lupeol can inhibit proliferation and induce apoptosis of human pancreatic cancer PCNA-1 cells through the Akt/ERK pathways." (PMID 31263453, 2019). "After the inhibitor treatment for 48 h, protein expression of PCNA was significantly down-regulated in pancreatic cancer cells, more in calponin 2 knockdown cells." (PMID 28915602, 2017). "In our previous study, co-treatment with NS-398, a selective COX-2 inhibitor, reversed the inhibitory effect on PCNA expression in human pancreatic cancer cells." (PMID 29190954, 2017). "Overall, these data suggest that embelin inhibited cell proliferation and induced apoptosis in pancreatic tumor tissues through inhibition of PCNA, Ki67, and activation of caspase-3 and cleavage of PARP." (PMID 24694877, 2014). "QRT-PCR was performed to evaluate the levels Shh, Gli1, IGFBP6, IGF2, PCNA, Bcl-2, Bax and Bak1 mRNA in pancreatic cancer tissues (n = 6) and corresponding cancer side tissues (n = 6)." (PMID 19736394, 2009). "In pancreatic cancer, decreased levelsof PCNA were linked with alterations in the NRF2 pathway, while alterationsin the MYC/MYCN and HIPPO pathways was linked with increased PCNAlevels in lung and pancreatic cancer." (PMID 40657100, 2025). "Creating multi‐marker panels including several biomarkers, such as PCNA, cyclin D1, and Ki‐67, may be a better way to predict patient outcomes and direct therapy choices for pancreatic cancer." (PMID 40051490, 2025). "Additionally, a study on pancreatic cancer and CDC26 showed that CCDC26 was responsible for the growth and apoptosis of pancreatic cancer cells, partly by regulating PCNA and Bcl2 expression." (PMID 31619233, 2019). "While PCNA is a marker of cellular proliferation, HIF1α has been shown to be associated with negative prognosis of several cancers including pancreatic cancer." (PMID 25929337, 2015). "Thus, PCNA mRNA decreasing suggests that Hh signaling promotes proliferation of pancreatic cancer cells." (PMID 19736394, 2009). "Additionally, pancreatic cancer cells showing PCNA expression are related to poor prognosis." (PMID 40051490, 2025). "In studies on pancreatic cancer, it was observed that silencing LINC01410 expression resulted in a decrease in IFITM3 protein levels in BxPC-3 cells, along with a downregulation of cell proliferation-associated proteins, including CDK6, Cyclin D2, and proliferating cell nuclear antigen (PCNA)." (PMID 41472748, 2025). "Proliferative markers (Ki‐67, PCNA, Cyclin D1, PHH3) serve as valuable indicators of pancreatic cancer behavior and treatment response." (PMID 40051490, 2025). "Previous studies have shown that silencing PROK1 exerts its anti-pancreatic cancer effects by inhibiting the PI3K/AKT/mTOR pathway, leading to increased levels of Bax and Cleaved Caspase 3, and decreased levels of PCNA and Bcl-2 in pancreatic cancer cells." (PMID 40961099, 2025). "IHC staining demonstrated significantly reduced expression of Ki67 and PCNA following ZQJ29 and OXA treatment, suggesting that ZQJ29 effectively suppressed pancreatic cancer progression." (PMID 40387570, 2025).